CDK4 (cyclin dependent kinase 4)
Diseases named in the same sentence as CDK4 in open-access papers (continued):
Sharing a sentence is not in itself a finding about the gene and the disease.
tumor (continued). "Finally, it is worth to mention that the effects of CDK4/6 inhibition on the patients’ immune system and tumor metabolism could be quite different in these two different stages of diseases." (PMID 39800748, 2025). "It has been shown that CDK4/CDK6 inhibitors could have an essential role in tumor growth." (PMID 40075679, 2025). "Moreover, HIF-2α and CDK4/6 inhibition may have a synergic antiproliferative effect on tumor cells, most probably by modulation of the tumor cells’ transition to the G1 phase." (PMID 40227577, 2025). "Although CDK4/6is have been reported to increase PD-L1 on tumor cells, this effect has not been clearly linked to IFN-γ signaling; nonetheless, prolonged IFN-γ exposure, which can induce a T cell exhaustion phenotype, remains a plausible contributor to PD-L1 upregulation." (PMID 41463246, 2025). "Since the reconstitution of YAP1 could not completely restore the malignant phenotypes caused by the inhibition of CDK4/6 in HCC cells, it is noteworthy that we cannot rule out the possibility of additional mechanisms involved in CDK4/6-mediated tumor progression of HCC." (PMID 40307228, 2025). "In addition to CDK4/6is, inhibiting other cyclin-dependent kinases can also affect tumor immunity." (PMID 41463246, 2025). "Thus, CDK4/6is-driven PD-L1 elevation exemplifies the drugs’ dualistic effects on tumor immunity." (PMID 41463246, 2025). "However, the concomitant targeting of the PAM, CDK4/6, and ER pathways likely affects other cellular functions that could contribute to tumor growth inhibition." (PMID 40565304, 2025). "Of note, the scope of CDK4/6-based therapy goes beyond targeting the tumour compartment as it exerts a critical function on the TME by promoting metabolic reprogramming and tumour immunity, which might improve the efficacy of metabolic therapy or immune checkpoint blockade." (PMID 40764669, 2025). "Notably, CDK4/6is exert anti-tumor immune effects by enhancing tumor antigen presentation, mediating the senescence phenotype that activates the immune system, inducing immunogenic cell death, enhancing T cell infiltration and activation, and reducing immunosuppressive cells." (PMID 41463246, 2025). "Pairing DNMT inhibition with CDK4/6 inhibitors may couple tumor-intrinsic restoration of antigen presentation to favorable immune remodeling, as CDK4/6 blockade increases tumor cell antigen-presentation gene expression and reduces regulatory T-cell proliferation, enhancing cytotoxic responses." (PMID 41383594, 2025). "Thus, CDK4/6is have also been shown to influence anti-tumor immunity." (PMID 41463246, 2025). "recently reported that tumor growth in the 4T1 model could be abrogated by promoting a hotter TIME when blocking Tyro3, Axl, MerTK, and Met with the small molecule inhibitor sitravatinib and that this blockade enhances the anti-tumor effect of CDK4/6 inhibition." (PMID 40391157, 2025). "Additionally, some tumor cells may bypass CDK4/6 inhibition by upregulating the Cyclin E-CDK2 complex, which is another important mechanism underlying tumor cell resistance." (PMID 41280894, 2025). "A potential drawback of the UPS tumour slices is the decreasing cell proliferation rate within the tissue over time, which could underestimate the efficacy of compounds targeting the cell cycle, such as CDK4/6 inhibitors." (PMID 40415599, 2025). "Additionally, inhibition of the PAM pathway has been found to increase cyclin D1 and CDK4/6 activity, which promotes proliferative cell cycling and can either increase sensitivity to CDK4/6 inhibition or restore sensitivity in tumor cells that have become resistant to CDK4/6 inhibition." (PMID 40711480, 2025). "In addition, CDK4/6is also reduced the presence of tumor-infiltrating immunosuppressive CD11c+ myeloid cells, which might be attributed to inhibiting the proliferation of bone marrow hematopoietic progenitors." (PMID 39593745, 2024).
tumor (continued). "Additionally, the immunohistochemical analysis indicated reduced expression of Ki67, MMP9, Cyclin D1, and CDK4 in the tumor tissues of CMHE-treated mice, implying the repression of the proliferative and metastatic ability of cancer cells in the tumor tissues by CMHE treatment." (PMID 39161904, 2024). "We investigated whether we could identify a panel of miRNAs associated with response to treatment in tumor tissues of patients with Hormone Receptor-positive/HER2-negative metastatic breast cancer treated with endocrine therapy (ET) and the CDK4/6 inhibitor (CDK4/6i)i palbociclib." (PMID 38338777, 2024). "Finally, we wanted to assess the effect of CDK4/6 inhibition on multicellular 3D tumour spheroids." (PMID 41146951, 2024). "CDK4 amplification stimulates the pRb signaling pathway, which is related to the cell cycle, and may contribute, at least in part, to tumor growth in these groups of neoplasms." (PMID 39368400, 2024). "Additionally, targeting CDK4 activity to modulate tumor-suppression SMAD3 may represent a promising strategy for cancer patients." (PMID 38528618, 2024). "It has been shown that increased TK1 mRNA levels in the plasma-derived sEVs are also associated with clinical resistance to CDK4/6 inhibitors in metastatic breast cancer patients, which agrees with our data, and strengthen the plausibility of TK1 as a reliable tool for determining tumor progression." (PMID 39006942, 2024). "CdK4/6i prevent DNA replication by blocking progression from the G1 to S phase during cell division and tumor cell proliferation, meaning that they arrest tumor growth rather than causing significant tumor cell death." (PMID 38982546, 2024). "The degradation of CDK4/6 also augmented the efficacy of immune checkpoint blockades, through the upregulation of programmed cell death-ligand 1 (PD-L1) expression in cancer cells and the suppression of regulatory T cells cell proliferation in tumor microenvironment." (PMID 39419977, 2024). "In addition, the kinase activity of CDK4 was also significantly greater in the S-III subtype and was positively correlated with the MGPS, suggesting that CDK4 might promote tumor cell proliferation in the S-II subtype through phosphorylation." (PMID 39039072, 2024). "Studying the impact of novel therapies on tumors that have acquired resistance to CDK4/6i in vivo is challenging, as there are few if any animal models mimicking the most common clinical scenario – namely, a period of response to CDK4/6 inhibition followed by eventual tumor outgrowth." (PMID 38047585, 2024). "Moreover, increasing evidence has indicated that CDK4/6is not only have an anticancer effect but also promote tumor immune escape, which might contribute to drug resistance." (PMID 39593745, 2024). "Moreover, the inhibition of CDK4/CDK6 has been shown to effectively reduce MM tumor burden." (PMID 39664374, 2024). "Additionally, CDK4/6i have shown the ability to enhance anti-tumor immune responses." (PMID 38409585, 2024). "CDK4/6 inhibitors efficiently and accurately inhibit the activity of CDK4/6 kinases in BC cells to block the phosphorylation of retinoblastoma protein, thus blocking the progression of the cell cycle from the G1 to the S phase, in turn inhibiting the proliferation of tumor cells." (PMID 39247493, 2024). "Therefore, it is critical to elucidate the relationship between the CDK4/6–cyclin D1 complex and the tumor microenvironment components after CDK4/6i treatment, namely, how these inhibitors induce favorable immunotherapeutic effects, or the reverse, in patients." (PMID 39593745, 2024).
tumor (continued). "The combination of PIN1 inhibitor and CDK4 inhibitor thus enhances anti-tumor immunity, with decreased Tregs, increased cytotoxic T cells and evidence for tumor cell phagocytosis, raising the possibility that this rewiring of the immune system could further improve the therapeutic effect." (PMID 38622115, 2024). "Nevertheless, a minority of intrinsically CDK4/6i insensitive tumours lacking CDK4 phosphorylation and associated with poor survival might have to be identified." (PMID 36453028, 2024). "The data suggest that CDK2 targeting in low-CDK4/6 tumours may be a clinical strategy." (PMID 38732271, 2024). "Therefore, there is a need for non-invasive tools to quantify CDK4/6 target engagement to ensure that CDK4/6 inhibitors reach concentrations in the brain sufficient to elicit pharmacological effects in tumor tissues and to provide information on response to treatment in real time." (PMID 38999983, 2024). "Combined Palbociclib inhibition of CDK4/6 further enhanced the effect of Talazoparib, while PD-L1 antibody could enhance the activity of anti-tumor T cells by inhibiting the immune escape of tumor cells." (PMID 39867908, 2024). "Hence, CDK4 T172-phosphorylation might be the most relevant biomarker of potential tumor sensitivity to CDK4/6i, by identifying or predicting the presence of active CDK4, which is the actual target of inhibitory drugs." (PMID 37964967, 2023). "To test our hypothesis, we conducted an open-label, multicenter clinical trial and mapped functional activation and signaling architecture of pretreatment tumor tissue biopsies collected from HR+/HER2− MBC patients receiving first-line treatment with a CDK4/6 inhibitor plus ET." (PMID 36797347, 2023). "To determine if CDK4/6 inhibition could reduce skeletal tumour growth, we first investigated the effects of palbociclib on the early stages (defined as growth of disseminated tumour cells in bone) of bone metastasis from ER+ primary tumours in vivo." (PMID 37190140, 2023). "Palbociclib, which is particularly confined to the ATP binding location of CDK4/6 proteins, prevents Rb phosphorylation, inhibits E2F transcription factor release, and blocks the cell cycle between G1 and S phases, and ultimately cease the growth of tumor cells." (PMID 37228871, 2023). "For example, CDK4/6 inhibition was shown to enhance antigen presentation, which accompanied an increased IFNγ response; interestingly, the authors linked this outcome with downregulation of DNMT1, hypomethylation of TEs, and enhanced chemokine secretion that stimulated tumor immune surveillance." (PMID 37055433, 2023). "In order to validate Pak1 as a marker of acquired mechanisms of resistance also in patients’ cohort, the evaluation of PAK1 expression might be investigated in future studies in tumor biopsies of patients with disease progression after ER+ plus CDK4/6i therapy." (PMID 37258566, 2023). "Therefore, our findings suggest that CDK4/6 inhibitors may enhance anti-tumor immunity through the STING-dependent type I interferon response." (PMID 37833461, 2023). "Several preclinical studies described that CDK4/6i themselves could boost antitumor immune responses in BC and other cancers, driven by T cell-intrinsic mechanisms as well as enhancement of antigen presentation in tumor cells." (PMID 37835528, 2023). "Other than CDK4 inhibition, we also found some reported or new tumor suppressor genes that may potentially regulated by EZH2 degradation induced by IHMT-337 in our transcriptomic data, suggesting IHMT-337 induced degradation of EZH2 results in complicated transcriptional regulation." (PMID 36642705, 2023). "Additionally, research revealed that tumor cells resistant to CDK4/6i could continue to rely on the ER pathway to drive tumor growth." (PMID 37580832, 2023). "Moreover, restoration of RB1 expression was able to restore tumor cells’ sensitivity to CDK4/6i." (PMID 37835528, 2023).
tumor (continued). "Hence, we speculate that PFKFB4 plays a prominent role in tumour cell stemness transformation and acquired CDK4/6 inhibitor resistance and targeting PFKFB4 might be an ideal strategy for ER+ BC chemotherapy." (PMID 36127291, 2023). "Consequently, CDK4/6 inhibition could restore the sensitivity of drug-resistant tumor cells to the effects of HER2 inhibitors." (PMID 37160904, 2023). "However, combinatorial treatment with a CDK4/i and an ERK-MAPK inhibitor synergistically suppresses tumor growth through blocking CDK4/6i-induced compensatory upregulation of ERK, PI3K, antiapoptotic signaling, and MYC expression in PDAC cell lines and organoids." (PMID 38263982, 2023). "We found that Cdk4−/− tumor could grow at a similar rate as vector cells and Cdk6−/− tumor could grow to bigger size in Ifnar1−/− mice than those in WT C57 mice, suggesting the important role of IFNAR-1 in TME for the anti-tumor immunity activated in Cdk4−/− and Cdk6−/− cancer cells." (PMID 37833461, 2023). "However, while anti-CDK4 monotherapy is associated with limited response, preclinical models have suggested overexpression of CDK4 may lead to induced expression of PD-L1 by tumor cells, paving the way to employ possible combination targeted therapy regimens." (PMID 36826126, 2023). "Tumor type and RB1 context may affect exactly how FOXM1 expression influences CDK4/6 inhibitor efficacy, meriting further investigation, but there is growing evidence that FOXM1 plays a key role in determining tumor cell responsiveness and resistance to CDK4/6 targeting." (PMID 37686402, 2023). "Although we observed a significant increase in ERK1/2 in palbociclib-sensitive tumours (compared to vehicle), this could be a compensatory mechanism to overcome cell cycle arrest; however, since the CDK4/6 pathway is downstream of this, palbociclib still exerts its inhibitory effect." (PMID 37190140, 2023). "In contrast to this, new research has shown that CDK4/6 inhibition may support tumour immune evasion in a number of tumour types through the increase of the immunosuppressive programmed cell death protein 1 ligand (PD-L1) expression on tumour cells." (PMID 36768557, 2023). "While only a small proportion of these BRCA1-like tumour harboured BRCA1 germline mutation, the finding that FOXM1 and downstream factors CDK4/6 are highly expressed in BRCA1-like tumours may have predictive implications in the setting of available CDK4/6-based therapies in BRCA1/2mut cancers." (PMID 36831687, 2023). "Importantly, correlation analysis revealed the MGPSs were positive correlated with the expression of CDK4/6 and negatively correlated with expression of CDKN2A/B, supporting the deletion of CDKN2A/B contribute to the tumor cell proliferation through activating CDK4/6." (PMID 36720864, 2023). "Pathological and WB analysis showed that the tumors in combination group exhibited apparent inhibition of CDK4/6 activity as the phosphorylation of RB (pRB, Ser807/811) in the combination group was efficiently reduced, suggesting an evident cell cycle arrest and tumor proliferation restriction." (PMID 36755269, 2023). "With the knowledge of the numerous effects of CDK4/6i therapy on tumor cells, Tregs, cytotoxic T cells, and even stem and progenitor cells, it is reasonable to assume that the pretreatment status of the tumor immunity may have predictive value." (PMID 38040730, 2023). "Furthermore, mapping drug target data to the top genes in our association prediction identifies inhibitors that could potentially enhance tumor response to anti-PD1, such as inhibitors of the encoded proteins of CDK4, GSK3B, and PTK2." (PMID 35013211, 2022).
tumor (continued). "Interestingly, ZC-22 displayed a better anti-tumor efficacy than the Olaparib and Abemaciclib monotherapy, and the combination therapy in cell culture models, suggesting that ZC-22 was a potential alternative for the PARPi and CDK4/6i combination therapy." (PMID 35270034, 2022). "Therefore, CDK4/6 enzymes are considered promising targets in cancer therapy, and the anti-tumor effect of small molecule CDK4/6 inhibitors is based on blocking the phosphorylation of the tumor suppressor retinoblastoma (Rb), and induction of G1/S arrest in tumor cells." (PMID 35938171, 2022). "Furthermore, both tumor subtypes were resistant to CDK4/6 inhibition." (PMID 36333737, 2022). "Additionally, given the efficacy of CDK4/6 inhibitors in certain types of cancers harboring SMARCA4 loss, we highlight that the deletion and nonsense variants in CDKN2A (p16) were found in 30% and 35% of our tumor samples, respectively." (PMID 35884575, 2022). "Furthermore, LOC441204 activated by the β-Catenin/p21/CDK4 pathway could promote the growth of tumor cells." (PMID 36059706, 2022). "The fact that abnormal PI3K-mTOR as well as MAPK signaling are observed in multiple tumor types that exhibit do novo or acquired resistance to CDK4/6 inhibitors [reviewed in 191, 192] suggests that targeting these pathways might be of significant clinical value." (PMID 36051751, 2022). "However, in some contexts, the specific immunomodulatory effects of CDK4/6i may impinge on anti-tumor immunity." (PMID 35444175, 2022). "CDK4 might be another key factor in PAQR4-mediated tumor progression." (PMID 36481756, 2022). "Importantly, patients who have previously failed ICI therapy should be considered as eligible for CDK4/6i-ICI combination trials, given the capacity for CDK4/6i to directly induce both tumor- and CTL-intrinsic transcriptional signatures associated with favorable ICI responses." (PMID 35444175, 2022). "In breast and other solid tumors, CDK4/6 inhibitors could trigger anti-tumour immune responses." (PMID 36266723, 2022). "Both genotypes responded to MEK + CDK4/6 inhibition; however, ΔS tumors uniquely showed induction of necrosis detected by ultrasound, which was preceded by an early reduction in tumor size, increase in CD3e+ T-cell infiltration and engagement of an antitumor myeloid cell phenotype." (PMID 36344707, 2022). "Interestingly, a combination of OTX015 and abemaciclib (the most potent of the 3 clinically approved CDK4/6 inhibitors) exhibited remarkable efficacy and superior tumor regression compared with the current standard-of-care treatment of abemaciclib + fulvestrant." (PMID 35881485, 2022). "However, from a tumor-intrinsic perspective, whether shortening the CDK4/6i dosing schedule would significantly compromise the tumor-intrinsic efficacy of BRAFi/MEKi+CDK4/6i, in regards to maintaining RB activation, requires further investigation." (PMID 35444175, 2022). "Therapeutic response signatures/biomarkers CDK4/6 and bromodomain extraterminal domain proteins (BETs) were selected as proof-of-concept targets to explore mechanisms of tumor growth and validate anti-tumor response to small-molecule-inhibitor monotherapy in OS PDXs." (PMID 36612255, 2022). "Considering that transient CDK4/6 inhibition can also activate this T‐cell population, these effects could combine to enhance immune‐mediated tumour clearance." (PMID 35037284, 2022). "However, whether transient short-term CDK4/6i is also sufficient to promote a prolonged tumor-intrinsic ICI-responsive transcriptional program requires further investigation." (PMID 35444175, 2022).